METTL3 (methyltransferase 3, N6-adenosine-methyltransferase complex catalytic subunit)
Diseases named in the same sentence as METTL3 in open-access papers (continued):
Sharing a sentence is not in itself a finding about the gene and the disease.
infection (62 papers, 2016 to 2025). The state of being infected such as from the introduction of a foreign agent such as serum, vaccine, antigenic substance or organism. "Down‐regulation of METTL3 by RNA interference rescued the decrease in osteogenic markers caused by infection." (PMID 40889211, 2025). "Supporting this mechanism, infection with viruses bearing nuclear export signal mutations that prevent METTL3 cytoplasmic translocation, maintained IFN-β mRNA m6A modification and resulted in significantly elevated IFN-β expression." (PMID 41325422, 2025). "(d) Heat map of m6A peaks related to mTOR pathway in T47D cells infected with retrovirus encoding sgMETTL3 resistant METTL3-WT, METTL3-Δ198, METTL3-Δ238, or control vector (Vec) followed by another infection with sgMETTL3 or sgControl (sgCtrl)." (PMID 37589705, 2023). "Resultingly, the METTL3 gene in the PVN was knocked down by infection with adeno‐associated virus (AAV)‐mediated short hairpin RNA (shRNA)." (PMID 35040253, 2022). "METTL3 or METTL14 were knocked down by siRNA 48 h prior to infection, a time point that led to stable loss of both RNA and protein expression throughout the subsequent infection." (PMID 33243990, 2020). "(a) Cumulative distribution function of log2 peak intensity of m6A-modified sites in T47D cells infected with retrovirus encoding sgMETTL3 resistant METTL3-WT, METTL3-Δ198, METTL3-Δ238, or control vector (Vec) followed by another infection with sgMETTL3 or sgControl (sgCtrl)." (PMID 37589705, 2023). "However, several studies have reported that the m6A modification affected the inflammatory response in different diseases; therefore, we further confirmed the specificity for DDX5-mediated m6A-modified regulation of inflammatory response in Mettl3 cKO mice after infection with pathogenic bacteria." (PMID 38182816, 2024). "Quantification of METTL3 distribution confirmed the METTL3 localization shift from the nucleus to the cytoplasm upon infection." (PMID 41325422, 2025). "To date, METTL3 and m6A have been studied primarily in the context of viral m6A enrichment and cellular responses to infection under conditions that alter m6A levels on viral transcripts." (PMID 40214229, 2025). "BPIV3 infection of METTL3-overexpressing cells led to markedly elevated IFN-β mRNA levels compared to empty vector controls." (PMID 41325422, 2025). "Analysis results in this review suggest that METTL3 hampers antiviral immunity, worsens viral replication and infection, and disrupts immune tolerance; conversely, regulating METTL3 enhances antiviral immunity and facilitates viral clearance." (PMID 40196133, 2025). "MARC-145 cells were infected with PRRSV, and METTL3 protein levels were assessed via western blot at 12, 24, and 36 h post-infection." (PMID 40548751, 2025). "In contrast, infection with Japanese encephalitis virus (JEV) inhibited METTL3 expression in mouse brain tissue." (PMID 40573422, 2025). "Immediately after the viral challenge (0 h post-infection; 0 hpi), METTL3 was exclusively localized in the nucleus." (PMID 41325422, 2025). "We first determined the kinetics of m6A upregulation in response to X4-tropic HIV-1NL4-3 infection of Jurkat cells to identify the optimal time of infection at which to measure the METTL3/14 interaction." (PMID 41085277, 2025). "METTL3 also plays a regulatory role in macrophage function, which is crucial in the con text of infection-driven lung inflammation." (PMID 41515964, 2025). "Since paramyxoviruses replicate in the cytoplasm, the cellular distribution of METTL3 appears to be altered during infection." (PMID 41325422, 2025). "While METTL3 was exclusively nuclear in mock-infected cells, BPIV3 infection induced a striking translocation of METTL3 to the cytoplasm, where it was specifically recruited to inclusion bodies containing accumulated viral N proteins." (PMID 41325422, 2025).
infection (continued). "In this study, we aim to investigate the effects of butyrate therapy and changes in METTL3 expression on osteoblasts under infection conditions." (PMID 40889211, 2025). "The results showed that, during PRV (MOI = 0.4) infection, compared to the empty vector group, all METTL3 groups (METTL3, METTL3-S43A, METTL3-S50A, and METTL3-S525A) significantly enhanced the mRNA transcription levels of IL-1β, IL-8, IL-6 and TNF-α." (PMID 40802811, 2025). "Nevertheless, NiV-M infection tended to retain higher residual METTL3 levels and exhibited a greater degree of ALKBH5 suppression compared to NiV-B." (PMID 40573422, 2025). "Infection with H.pylori increases the expression of METTL3 in GC cells, thereby leading to the upregulation of STAT5A." (PMID 38879589, 2024). "The analysis of viral titer in the cellular supernatant 24 h post infection indicated that reduction of METTL3 expression led to an increase in CVB1 production." (PMID 39744389, 2024). "Intriguingly, SFTSV infection significantly increased the expression of METTL3, especially in the cytoplasm of cells where SFTSV replicated." (PMID 39585899, 2024). "Consistently, we observed significantly higher IL-6 levels in primary Mettl3 cKO BMDM compared to Mettl3 WT BMDM following infection with P. multocida and S. aureus for 0–12 h, and M. pneumoniae for 0–24 h, as well as TNF-α." (PMID 38182816, 2024). "A similar increase in TLR2 and p-p65 expression was detected in primary Mettl3 cKO BMDM during 0 ~ 36 h post-infection with M. pneumoniae and during 0–24 h post-infection with S. aureus." (PMID 38182816, 2024). "As the critical catalytic core of the m6A methyltransferase complex, METTL3 normally localizes in the nucleus of cells, and its abundance increases during the infection processes of various RNA and DNA viruses." (PMID 39585899, 2024). "And the levels of IL-6 and TNF-α were significantly higher in serum and lungs of Mettl3 cKO mice than those of Mettl3 WT mice upon infection with P. multocida, S. aureus, and M. pneumoniae." (PMID 38182816, 2024). "METTL3-mediated m6A modification amplifies the type I IFN responses during infection by VSV or HSV-1 by increasing the translation of IFN-stimulated genes." (PMID 39744389, 2024). "In this study, we found that infection with H. pylori increases the expression of METTL3 in GC cells, which is consistent with a recent report that infection with H. pylori can result in the upregulation of METTL3 in mouse models." (PMID 38879589, 2024). "First, primary BMDM from Mettl3 cKO and Mettl3 WT mice were collected and maintained in cell culture prior to infection with M. pneumoniae, S. aureus and P. multocida." (PMID 38182816, 2024). "Three days after infection, METTL3 expression was dramatically repressed at both mRNA and protein levels in rPASMCs treated with shMETTL3 compared to the shNC group." (PMID 38866991, 2024). "Conversely, infection with a lentiviral METTL3 RNAi construct led to significantly decreased METTL3 expression (p < 0.05)." (PMID 37569302, 2023). "AHR, peribronchial inflammation, goblet cell hyperplasia, and mucus secretion seen in Mettl3 KO mice were substantially diminished after infection with the shPtx3 lentiviruses." (PMID 37957139, 2023). "The catalytic activity of METTL3 is necessary for efficient viral RNA synthesis and protein accumulation within 24 hours of infection." (PMID 38035086, 2023). "We used qRT-PCR to confirm that METTL3 expression was significantly increased following infection of primary hepatocytes with a lentiviral METTL3 overexpression construct (p < 0.05)." (PMID 37569302, 2023). "After having demonstrated the importance of METTL3 for viral RNA synthesis using life cycle modelling systems, we next confirmed these data in the context of an infection with authentic EBOV." (PMID 37306620, 2023). "In all cases, the infection of METTL3- and YTHDF2-depleted cells led to enhanced IFNB and ISG15 expression." (PMID 37509095, 2023).
infection (continued). "In this study, we provide the first evidence that the m6A modification level was enhanced in macrophages in vitro after TP infection and that the writer, METTL3, and the reader, YTHDF1, were upregulated both in vitro and in secondary syphilitic lesions." (PMID 35444649, 2022). "Immunoblotting with antibodies targeting ALKBH5, FTO, METTL14 and METTL3 in ileum tissue from mice infected with RV EW or treated with PBS was carried out at 2 days post infection (dpi)." (PMID 35098923, 2022). "(i) qPCR analysis of the indicated genes in Rhesus rotavirus (RRV)-infected HT-29 cells transduced with Mettl3 single guide RNA (sgRNA) or control sgRNA, at the indicated hours post infection (hpi) (mean ± SEM)." (PMID 35098923, 2022). "RT-qPCR was performed on RNA extracted from cells collected at 72 h post infection (hpi), which confirmed effective silencing of METTL3 (75%) and METTL14 (85%)." (PMID 35725909, 2022). "This hinted that DDX5 inhibited innate immunity by interacting with METTL3 after infection with RNA virus." (PMID 33909701, 2021). "Transcriptome analyses showed that infection with influenza A virus upregulated the expression level of WTAP (two of six experiments) but downregulated METTL3, RBM15, and VIRMA (one of six experiments, each)." (PMID 34502037, 2021). "Short-read sequencing results showed that the overall abundance of all viral transcripts in late infection, except that of L152K, was reduced after METTL3 knockout." (PMID 34368152, 2021). "On day 5 post infection, forced expression of Mettl3-WT and Mettl3-Mut both resulted in elevated METTL3 expression in Mettl3fl/flCd4-Cre SMARTA cells compared with the empty-vector (EV) retrovirus." (PMID 33637761, 2021). "To further investigate the innate immunity pathways regulated by DDX5, we detected the expression of p-TBK1, p-IKKγ, p-p65, and p-IRF7 in DDX5- or METTL3-knockdown or -overexpressing MEFs after infection with VSV." (PMID 33909701, 2021). "Meanwhile, at 72 h post infection, the activated CD4+ T cells were mostly in the fifth and sixth divisions, whereas METTL3-deficient CD4+ T cells were dominant in third and fourth divisions." (PMID 33637761, 2021). "In influenza A virus (IAV) and respiratory syncytial virus (RSV), for which infection by either is characterized by respiratory symptoms, inactivation of METTL3 inhibited virus replication and pathogenesis." (PMID 33431045, 2021). "We counted full-length RNA transcripts after infection of METTL3 knockdown A549 cells normalized to the read depth of the experiment." (PMID 33243990, 2020). "After 24 h infection of A549 cells with Ad5 following knockdown of METTL3, nascent RNA was labeled with 4sU for the last 10 min of infection." (PMID 33243990, 2020). "Over the course of infection, levels of the assayed writers (METTL3, METTL14, and WTAP) and readers (YTHDC1, YTHDF1, and YTHDF2) remain unchanged." (PMID 33243990, 2020). "Western blot analysis revealed that the expression of METTL3 decreased in GC cells after infection with lentivirus expressing sh-METTL3." (PMID 33048840, 2020). "Intriguingly, knockdown of METTL3/14 enhanced infection while FTO depletion correspondingly reduced infection." (PMID 29259584, 2017). "In summary, METTL3 is a central epigenetic switch in infection-driven lung injury." (PMID 41515964, 2025). "Consistent with observations in NiV-infection, METTL3 enhanced m6A modification of NiV P mRNA." (PMID 40573422, 2025). "Overexpression of METTL3 prior to rBPIV3-EGFP infection significantly enhanced viral replication." (PMID 41325422, 2025). "We have showed that SFTSV infection induces the translocation of METTL3 from the nucleus to the cytoplasm, where it may interact with the translation initiation complex and thus enhances translation." (PMID 39585899, 2024).
infection (continued). "In addition, it seems that METTL3 is capable of promoting SFTSV infection in an m6A-independent fashion because the truncated METTL3 without the crucial catalytic site (DPPW motif) enhances SFTSV replication as well." (PMID 39585899, 2024). "In addition, there was a slight decrease in nuclear METTL3 levels after infection, accompanied by a corresponding increase in cytoplasmic METTL3." (PMID 39496835, 2024). "Moreover, infection with either respiratory syncytial virus (RSV) or vesicular stomatitis virus (VSV) promoted the expression of METTL3,84,85 whereas infection with Japanese encephalitis virus (JEV) inhibited METTL3 expression in mouse brain tissue." (PMID 39759074, 2024). "Notably, the knockdown of YTHDF2 and METTL3 proteins resulted in a decrease in viral replication at 24 hours post infection (hpi), which were consistent with a previous study." (PMID 37053288, 2023). "To assess whether the methylation of EBOV RNAs serves the same purpose, we performed minigenome assays and infections in parental, negCtrl and METTL3 KO cells and determined the levels of IFN-β mRNA in these cells." (PMID 37306620, 2023). "Indeed, upon infection, the host m6A machinery, including writers (METTL3-METTL14), erasers (ALKBH5, FTO), and readers (YTHDC1, YTHDF1-3), was found to be upregulated at both the RNA and protein levels." (PMID 36016289, 2022). "Additionally, differential methylation among the variants must be explored because experimental data with knockdown METTL3 viruses suggest that hypomethylated viral genomes are produced and the infection is significantly reduced." (PMID 34834915, 2021). "Immunoblot analysis of cell extracts harvested at 72 hr post-infection (hpi) revealed that METTL3+14 depletion significantly increased the abundance of the HCV NS5A protein, a marker of viral replication, relative to its level in cells treated with non-targeting control siRNA." (PMID 27773535, 2016). "However, these inhibitory effect of DAA on SFTSV infection was nearly abolished in METTL3 KO cells." (PMID 39585899, 2024). "METTL3-dependent loss of late gene splicing efficiency was independent of time post infection." (PMID 33243990, 2020). "In order to investigate the impact of HP on the expression of METTL3 and CXCL1, we co-cultured HP with human gastric epithelial cells (GES-1) at varying multiplicities of infection (MOI) for 24 h." (PMID 40825934, 2025). "In this study, we found that during infection with the prototypical alpha-herpesvirus Pseudorabies virus (PRV), ERK2 protein expression increased significantly, while METTL3 expression decreased both in vitro and in vivo." (PMID 40802811, 2025). "During the prolonged infection of S. aureus in MC3T3‐E1 cells, an up‐regulation of m6A methyltransferase METTL3 was observed, which exhibited an inverse relationship with osteogenic markers." (PMID 40889211, 2025). "The mRNA abundance of methyltransferase METTL3, and m6A-specific binding protein YTHDF2 and YTHDF3 significantly increased from 18 h to 24 h after infection." (PMID 40663568, 2025). "Our results revealed that all METTL3 groups (METTL3, METTL3-S43A, METTL3-S50A, and METTL3-S525A) significantly enhanced NF-κB promoter activity during PRV (MOI = 0.4) infection compared to the empty vector group." (PMID 40802811, 2025). "That study proposed that DDX5 regulates the interaction between METTL3 with its adaptor, METTL14, after infection." (PMID 40214229, 2025). "Accordingly, nuclear-cytoplasmic fractionation combined with WB analysis showed an increase of cytoplasmic METTL3 both in Huh7 cells and HEK293T cells upon SFTSV infection." (PMID 39585899, 2024). "Our objective was to detect the potential impact of silencing METTL3 on CVB1 amplification, so we set up infection conditions to avoid superinfection and excessive cell death." (PMID 39744389, 2024). "After silencing METTL3 or transfection with control siRNA, EndoC-βH1 cells were infected with CVB1 and collected 24 h post-infection." (PMID 39744389, 2024).
infection (continued). "HeLa cells were transfected with siRNAs targeting METTL3 or YTHDF2 to silence their expression, followed by infection with CVB3." (PMID 39597541, 2024). "Immunofluorescence results revealed that both METTL3 and ALKBH5 aggregated in the cytoplasm following infection (Fig. EV1A,C), while METTL14 remained localized in the nucleus before and after infection (Fig. EV1B)." (PMID 39496835, 2024). "The knockdown of METTL3 or METTL14 using shRNA in MT4 cells and the subsequent infection with the HIV-1 virus (clone LAI) led to a significant decrease in viral replication, as assessed by gp120 mRNA expression and p24 capsid protein levels." (PMID 37509095, 2023). "The knockout of METTL3 in A549 cells led to decreased NP, NS1, and M2 viral protein expression up to 72 h post-infection with the IAV-PR8 virus, in addition to significantly reduced infectious viral particle production." (PMID 37509095, 2023). "They observed that following the knockdown of METTL3 or YTHDF2, infection leads, through effects independent from the viral mechanisms, to the upregulation of many genes involved in the Type I IFN response, ultimately restricting viral proliferation." (PMID 37509095, 2023). "We were unable to reproducibly knock-down METTL3, but ALKBH5 was efficiently knocked down after infection with a lentivirus carrying shRNA to ALKBH5." (PMID 35190939, 2022). "In particular, both METTL3 and METTL14 were shown to promote HIV-1 replication in multiple round infection assays and to be required for efficient Gag protein expression in cells transfected with an HIV-1 proviral plasmid." (PMID 35101069, 2022). "METTL3 and METTL14 depletion led to increased expression of the HBc and HBs proteins, consequently promoting the progression of infection." (PMID 33431045, 2021). "Recent studies have shown that IFNβ mRNA contains m6A methylation and that the m6A level of IFNβ is reduced following repression of METTL3, stabilizing the IFNβ mRNA and leading to higher levels of IFN production upon infection by human cytomegalovirus (HCMV)." (PMID 34929018, 2021). "Depletion of METTL3 or METTL14 enhanced ZIKV infection in 293T cells whereas ALKBH5 and, to a lesser extent, FTO knockdown reduced infection." (PMID 29259584, 2017). "The treatment relative to infection was crucial to analyze as the effect of STM2457 is reversible; therefore, when removed from the medium, the cells may return to normal METTL3 activity." (PMID 40214229, 2025). "In contrast, infection with the M-K258R mutant virus failed to induce cytoplasmic translocation, and METTL3 remained restricted to the nucleus together with M-K258R." (PMID 41325422, 2025). "Moreover, the increased expression of TLR4 in the lungs of Mettl3 cKO mice upon infection with P. multocida and of TLR2 upon infection with S. aureus and M. pneumoniae were confirmed by immunohistochemistry staining." (PMID 38182816, 2024). "In keeping with these findings, the mRNA levels of METTL3 & METTL14 (m6A writers), ALKBH5 & FTO (m6A erasers), and YTHDF2 (m6A reader) were significantly increased in a time-dependent fashion in Huh7 cells post SFTSV infection." (PMID 39585899, 2024). "We infer that the inhibition of JEV replication in neuro2a cells upon METTL3 knockdown, observed at 48 hpi rather than 24 hpi, is not due to variations in host recognition, which occurs in the early stages post-infection." (PMID 38243270, 2024). "The negative effects on viral RNA synthesis due to loss of m6A methylation are independent of innate immune sensing, as METTL3 knockout did not affect type I interferon induction in response to viral RNA synthesis or infection." (PMID 37306620, 2023). "Collectively, this suggests that METTL3 depletion leads to the induction of inflammatory genes in response to infection with SARS-CoV-2 that is mostly independent of IFN-induction, irrespective of the cell type." (PMID 37509095, 2023).